CAV1 (caveolin 1)
Diseases named in the same sentence as CAV1 in open-access papers (continued):
Sharing a sentence is not in itself a finding about the gene and the disease.
Peritoneal Fibrosis (2 papers, 2015 to 2020). Disorder characterized by a wide range of structural changes in PERITONEUM, resulting from fibrogenic or inflammatory processes. "Interestingly, a prolonged activation of the TGF-β1 signaling may induce CAV1 downregulation, leading to an imbalance of this feedback regulation and promoting peritoneal fibrosis." (PMID 32811813, 2020). "Finally, a mouse peritoneal adhesion model demonstrated the relevance of CAV1 for curbing mechanical MMT and peritoneal fibrosis in vivo." (PMID 32811813, 2020). "The cell-division Ki67 marker was not significantly increased in Cav1−/− peritoneum upon exposure to PD fluid, indicating that the increased peritoneal fibrosis and angiogenesis in these animals were not directly related to increased cell proliferation during the analysis period." (PMID 25550395, 2015).
Pleural effusion (2 papers, 2022 to 2025). The presence of an excessive amount of fluid in the pleural cavity. "For comparison with other body fluids (i.e., plasma/serum, BAL, and pleural effusion), 153 out of 912 MV proteins were pleural effusion-specific proteins, including ABI1, BSG, CAV1, GRB2, RAS proteins, and SRC." (PMID 35158999, 2022).
prion disease (2 papers, 2015 to 2017). A transmissible disease that is caused by a protein that is able to induce abnormal folding of normal cellular proteins, leading to characteristic spongiform brain changes, which are associated with neuronal loss without an inflammatory response. "We recently reported that accumulation of PrPSc in prion diseases relates to internalization of TACE α-secretase in caveolin-1 (Cav-1)-enriched microvesicles caused by PDK1 overactivation, which cancels PrPC neuroprotective α-cleavage by TACE." (PMID 26241960, 2015). "Nevertheless, the possibility cannot be excluded that some of clinical symptoms or signs seen in the early or terminal stage of prion diseases may be associated with dysfunctions of caveolin-1 involved signal transduction due to loss of function of PrPC." (PMID 28903310, 2017). "Using Western blot analysis, we first investigated the distribution of caveolin-1 in different brain areas in normal individuals and patients with sporadic Creutzfeldt-Jakob disease (sCJD), the most common form of human prion disease." (PMID 28903310, 2017). "Therefore, neuronal loss in prion diseases may not be sufficient to cause changes in the levels of caveolin-1." (PMID 28903310, 2017).
prostate (2 papers, 2011 to 2012). "However, the expression of CAV1, IGFBP3 and TGFBR2 is decreased in PCa in general, suggesting a role in prostate carcinogenesis." (PMID 23185447, 2012).
Pseudomonas infection (2 papers, 2012 to 2017). Infections with bacteria of the genus pseudomonas. "Cav-1−/− mice and primary cultures of tracheal epithelial cells derived from these animals are strikingly resistant to Pseudomonas infection in vivo." (PMID 29250058, 2017). "Caveolin-1 and Cav-2 also show opposing effects regarding infections by the Gram-negative bacteria Pseudomonas aeruginosa, although one may observe that disparate results were obtained in in vivo studies of Pseudomonas infection, as it will be discussed next." (PMID 29250058, 2017).
Psoriasiform dermatitis (2 papers, 2019). A skin abnormality characterized by redness and irritation, with thick, red skin that displays flaky, silver-white patches (scales). "Cav-1 expression is strongly reduced in psoriatic skin, and induced expression of Cav-1 leads to substantial improvement of psoriasiform dermatitis in mice." (PMID 30729030, 2019).
Pulmonary capillary hemangiomatosis (2 papers, 2016 to 2019). Pulmonary capillary hemangiomatosis (PCH) is a rare form of pulmonary arterial hypertension (PAH, see this term) characterized by a capillary infiltration of the pulmonary interstitium, bronchioles and pleura leading to elevated pulmonary arterial resistance and right heart failure. "Three African American and 16 Caucasian patients, including 1 with pulmonary veno-occlusive disease and 1 with pulmonary capillary hemangiomatosis, had mutations in the bone morphogenetic protein receptor type 2 (BMPR2), Caveolin 1 (CAV1) or EIF2AK4 gene." (PMID 27224443, 2016).
renal tumours (2 papers, 2003 to 2008). "We conclude that evaluation of the ‘caveolin-1/AKT/mTOR axis’ in primary kidney tumours will identify subsets of RCC patients who require greater postoperative surveillance and more intensive treatment." (PMID 18283322, 2008). "Using multivariate Cox proportional hazard regression models, we evaluated whether the coexpression of caveolin-1 and pAKT could be of prognostic value in the assessment of primary renal tumours." (PMID 18283322, 2008). "Determination of the degree of caveolin-1 expression in these tumour fragments may be of additional value in the staging of renal tumours and assessment of prognosis." (PMID 14612902, 2003). "However, from what is currently known from other studies, caveolin-1 may serve as an important intercellular signalling molecule that is capable of potentiating the progression, invasiveness and vascularisation of renal tumours." (PMID 14612902, 2003).
respiratory distress syndrome (2 papers, 2020 to 2021). "In addition, the lung sections from infants with respiratory distress syndrome show that the presence of increased pulmonary artery pressure unaccompanied by endothelial damage does not result in the loss of endothelial CAV1 or enhanced expression of CAV1 in VSMC." (PMID 31979420, 2020). "In infants with respiratory distress syndrome, despite PH and significant medial thickening, the expression of endothelial caveolin-1, PECAM-1, and vWF in pulmonary arteries was reported as well preserved, without any evidence of EC disruption or enhanced expression of cav-1 in SMC." (PMID 34698188, 2021).
salivary gland tumors (2 papers, 2021 to 2024). "According to the authors, these findings indicate a significant role of Caveolin-1 in the development of salivary gland tumors and its potential use as a diagnostic biomarker." (PMID 39684268, 2024).
schistosomiasis (2 papers, 2011 to 2023). An infectious disease caused by parasitic trematodes of the genus Schistosoma that colonize human blood vessels and release eggs that can cause granulomatous reactions leading to acute (swimmer's itch or acute schistosomiasis syndrome) or chronic disease. "However, schistosomiasis did not alter the expression of caveolin-1." (PMID 21853150, 2011).
silicosis (2 papers, 2022 to 2025). Silicosis is a respiratory disease caused by breathing in (inhaling) silica dust. "Based on Masson staining and IHC staining of collagen I, Cav‐1 deficiency aggravated diffuse fibrosis in silicosis, further confirmed in the WB analysis of collagen I." (PMID 34889029, 2022). "Based on HE staining, Cav‐1 deficiency significantly aggravated lung structural remodelling and silicotic nodules formation in silicosis." (PMID 34889029, 2022). "Caveolin 1 (CAV1) involves many crucial processes in silicosis-induced LF, including fibroblast activation, oxidative stress, and inflammation." (PMID 40504442, 2025). "In silica-exposed cells and silicosis models, overexpression of miR-552-3p enriched with CAV1 was reduced, while the fibrotic markers such as fibronectin and α-SMA were escalated." (PMID 40504442, 2025). "The silicosis model was established in WT mice for 7 and 28 days to detect the Cav‐1 level in silicosis." (PMID 34889029, 2022). "The silicosis severity increased in the lungs of silicotic Cav‐1−/− group than the silicotic nodules score (p < 0.05) and Ashcroft score (3.53 ± 0.81 vs. 5.29 ± 0.99, p < 0.05) of silicotic WT mice." (PMID 34889029, 2022). "In vivo and in vitro experiments established that Cav‐1 negatively regulates NF‐κB pathway in silicosis." (PMID 34889029, 2022). "Paraffin‐embedded sections of lung tissues from nine patients with silicosis and nine cases of tumour‐adjacent tissues used as control were collected, and immunohistochemistry (IHC) was performed to measure the Cav‐1 expression." (PMID 34889029, 2022). "It was found that Cav‐1 levels were significantly reduced in the lung from silicosis patients and silicotic mice." (PMID 34889029, 2022). "The silicosis models were established in C57BL/6 (wild‐type) and Cav‐1 deficiency (Cav‐1−/−) mice, and Cav‐1−/− mice displayed wider alveolar septa, increased collagen deposition and more silicotic nodules." (PMID 34889029, 2022). "It was firstly found in this study that Cav‐1 levels were significantly reduced in the lung from silicosis patients and silicotic mice." (PMID 34889029, 2022). "The IHC staining showed that the Cav‐1 level was high in normal tumour‐adjacent tissues but significantly decreased in silicosis lung tissues (p < 0.0001)." (PMID 34889029, 2022). "The mice peritoneal‐derived macrophages were used to explore the role of Cav‐1 in silica‐induced inflammation, which plays a central role in mechanism of silicosis." (PMID 34889029, 2022). "The silicosis model was established in WT and Cav‐1−/− mice for 28 day." (PMID 34889029, 2022). "Cav‐1 regulation is a potential treatment approach for silicosis." (PMID 34889029, 2022). "The results showed that Cav‐1 protected against lung injury in silicosis." (PMID 34889029, 2022). "Cav‐1 significantly reduced in the lungs of silicosis patients and silicotic mice." (PMID 34889029, 2022). "This study suggests reduced Cav‐1 involved in the silicosis progression." (PMID 34889029, 2022). "Therefore, this study aimed to elucidate the function of Cav‐1 in silicosis." (PMID 34889029, 2022). "Thus, this study evaluated Cav‐1 regulatory effects in silicosis." (PMID 34889029, 2022). "Therefore, Cav‐1 has an essential protective effect in silicosis." (PMID 34889029, 2022). "Recent studies revealed the anti‐inflammatory and anti‐fibrosis role of Caveolin‐1 (Cav‐1) in lung, but this role in silicosis has not been investigated." (PMID 34889029, 2022).
skin aging (2 papers, 2020 to 2021). The gradual irreversible changes in structure of skin that occur as a result of the passage of time.. "Total rat brain levels of Cav-1 are decreased in aged animals, and skin fibroblasts upregulate Cav-1 in both chronological and UV-induced skin aging." (PMID 33195223, 2020). "Modulation of Cav-1 can be provided both by a mild hyperthermia and/or mechanical stimulation, and it was considered as an important target in different inflammatory and hyperproliferative dermatological conditions as well as in prevention and therapy of skin aging." (PMID 34671678, 2021).
synucleinopathies (2 papers, 2011 to 2022). "Such physical interaction between CAV-1 and α-synuclein may regulate α-synuclein-mediated actions on cell death, processes known to be involved in synucleinopathies." (PMID 22128235, 2011). "Finally, transcripts known to be involved in Tau- and synucleinopathies include IGLON5, CAV1, GFRA2, SYNGR3, and SLC6A3, with the latter being particularly interesting as its genetic variants lead to Parkinsonism-dystonia infantile (PKDYS) syndrome." (PMID 35883433, 2022).
tauopathy (2 papers, 2021). Neurodegenerative disorders involving deposition of abnormal tau protein isoforms (tau proteins) in neurons and glial cells in the brain. "Co-staining of the dendritic marker MAP2 with Cav-1 showed decreased MAP2 expression in the hippocampal CA1 subfield and cortex in PSAPP-SynRFP, similar to that observed in postmortem human brains of patients diagnosed with CTE, tauopathy, and AD." (PMID 33981778, 2021).
thrombotic microangiopathy (2 papers, 2021 to 2022). The syndromes of microangiopathic hemolytic anemia, thrombocytopenia, and variable signs of organ impairment, due to platelet aggregation in the microcirculation. "In our experience (unpublished data), Cav-1 is also expressed in transplant and native kidney biopsies showing features consistent with chronic/active thrombotic microangiopathy (TMA) and exhibiting a staining pattern similar to c-ABMR." (PMID 34680435, 2021). "Additionally, Caveolin-1 (Cav1) was tested for in Case 2 as a marker of thrombotic microangiopathy (TMA)." (PMID 35204798, 2022).
thyroid neoplasms (2 papers, 2002 to 2014). "In this study, we investigated caveolin-1 expression in various types of thyroid neoplasm in order to clarify its role, including this point." (PMID 11953823, 2002). "In this study, we investigated caveolin-1 expression in thyroid neoplasms by means of immunohistochemistry using a rabbit polyclonal antibody against caveolin-1." (PMID 11953823, 2002). "To explore the mechanisms underlying the effect of gravity on thyroid protein fraction, we examined proteins relevant for the thyroid function; Caveolin-1 which is a critical protein to caveolae and STAT3 which is a suppressor of thyroid tumor growth." (PMID 24866829, 2014).
tongue cancer (2 papers, 2015 to 2022). A malignant neoplasm affecting the tongue. "This is the first report to show that tongue cancer cells use exosomes for transferring CAV1 to the TME and that these exosomes are apparently ingested by different types of cells within the TME, such as CAFs." (PMID 25633184, 2015). "Collectively, we suggest that, similarly to other types of carcinomas (e.g., breast, kidney and colon), CAV1 accumulates within the CAFs in tongue cancer as well." (PMID 25633184, 2015). "The present study is the first to investigate the accumulation of CAV1 in cancer cells and TME components in a series of tongue cancer cases and its association with clinical outcome." (PMID 25633184, 2015). "Prior to monoculturing HSC-3 tongue cancer cells, the model underwent modifications in oxygenation level (1%O2 hypoxia to upregulate CAV1) and/or in the amount of natural soluble factors [deleted by 14-day rinsing (rinsed myoma, RM), to allow only HSC-3-derived factors to act]." (PMID 25633184, 2015). "Among them, AC099850.3 is the most co-expressed lncRNA, which is related to six differently expressed mRNAs, namely (CAV1, NRAS, ACSL3, AURKA, EIF2AK4 and RRM2), and its high expression level is closely related to the reduction in the survival rate of patients with tongue cancer." (PMID 35299954, 2022).
Uterine leiomyoma (2 papers, 2019 to 2021). The presence of a leiomyoma of the uterus. "Moreover, the positive rate of caveolin 1 in the internal tissues of intravenous leiomyomatosis was high compared with that in normal uterine leiomyoma." (PMID 34563053, 2021). "In uterine leiomyomas, Cav-1 is down-regulated compared to normal myometrial tissues, suggesting that low expression levels of Cav-1 may promote the pathological process." (PMID 31759347, 2019).
vascular neoplasm (2 papers, 2013 to 2026). A benign, intermediate, or malignant neoplasm arising from vascular tissue including arteries, veins, venous sinuses, lymphatic vessels, arterioles and capillaries. "Caveolin-1 expression has been described in a range of vascular neoplasms, and caveolin-1 in endothelial cells regulates microvascular permeability." (PMID 23714181, 2013).
Ventricular arrhythmia (2 papers, 2022 to 2025). "S-nitrosylation of caveolin-1 heightens the risk of ventricular arrhythmia, whereas S-nitrosylation of RyR2, SERCA2, S100-A1, and L-type Ca2+ channels supports cardiac rhythm stability." (PMID 40867518, 2025). "In contrast to caveolin-3, myocardial caveolin-1 is correlated with left ventricular conduction velocity, and mice with caveolin-1 deficiency exhibit a heightened susceptibility to ventricular arrhythmias." (PMID 40867518, 2025). "Further studies have shown that, when cardiac RAAS activity is enhanced, the dissociation of CAV1 from cSrc leads to cSrc activation, impaired gap junction function, and increased tendency toward ventricular arrhythmia and sudden cardiac death." (PMID 35498046, 2022).
acute myeloid leukemia (1 paper, 2015). Acute myeloid leukemia (AML) is a group of neoplasms arising from precursor cells committed to the myeloid cell-line differentiation. "Research indicated that Cav-1 expression was positively correlated to ABCB1 in various cancers such as acute myeloid leukemia." (PMID 26431273, 2015). "Clinical studies indicated a positive correlation between Cav-1 and ABCB1 mRNA in acute myeloid leukemia independent of tumor stage." (PMID 26431273, 2015).
acute pancreatitis (1 paper, 2018). An acute inflammatory process that leads to necrosis of the pancreatic parenchyma. "CAV1-YAP regulation modulates pathophysiological processes such as ECM remodeling and the response to acute pancreatitis." (PMID 30404014, 2018).
adenomyosis (1 paper, 2019). The growth of endometrial tissue inside the muscular wall of the uterine corpus. "A study evaluated the expression of CAV 1 in the ESCs in the human uterus affected by adenomyosis and concluded that loss of stromal CAV1 expression may play a critical role in the pathogenesis of adenomyosis." (PMID 30388215, 2019).
age (1 paper, 2012). A temporal measurement of the time period elapsed since an identifiable point in the life cycle of an organism. "It has also been shown that Cav1 is involved in spatial memory formation and synaptic plasticity, and especially plays a role in age-related working memory decline." (PMID 22359574, 2012).
Airway obstruction (1 paper, 2015). Obstruction of conducting airways of the lung. "Airway obstruction and hyperresponsiveness correlated with the degree of increased caveolin-1 expression in ASM cells (P < 0.05; r = 0.69 and −0.52, respectively)." (PMID 25977751, 2015).
Aland island eye disease (1 paper, 2020). An X-linked recessive retinal disease characterized by fundus hypopigmentation, decrased visual acuity, nystagmus, astigmatism, progressive axial myopia, defective dark adaptation and protanopia. "An intronic-exonic deletion of 425bp encompassing exon 30 and adjacent introns of CACNA1F resulted in the deletion of the TM domain and extracellular loop of Cav1.4α1 in a patient with Aland Island eye disease (AIED), a nearly identical disorder to CSNB2." (PMID 32967234, 2020).
ameloblastic carcinoma (1 paper, 2021). A rare, cytologically malignant ameloblastoma that may metastasize. "The expression of caveolin-1 was evaluated in samples of the normal gingival epithelium (n=7), human tooth germ (TG) (n=12), ameloblastoma (AM) (n=83), and ameloblastic carcinoma (AC) (n=9) by immunohistochemistry." (PMID 33037799, 2021). "Key words:Ameloblastoma, ameloblastic carcinoma, caveolin-1, immunohistochemistry, real-time polymerase chain reaction." (PMID 33037799, 2021).
Aortic root aneurysm (1 paper, 2024). An abnormal localized widening (dilatation) of the aortic root. "However, the role of Cav1 in MFS-associated aortic root aneurysms has yet to be investigated." (PMID 39684412, 2024). "Cav1’s regulatory influence on aortic root aneurysm development in MFS through NO-mediated modulation of smooth muscle and endothelial function, with notable sex-dependent variations." (PMID 39684412, 2024). "Additionally, genes involved in ECM organization and inflammatory responses to injury (e.g., aortic root aneurysm) might be regulated differently in females than in males, leading to sex-dependent outcomes following Cav1 deletion." (PMID 39684412, 2024).
autoimmune myocarditis (1 paper, 2025). Autoimmune myocarditis is an autoimmune disease that affects the heart. "This differential expression suggests that Cav‐1's role in stimulating second signaling molecules in macrophages and some cardiomyocytes may contribute to cell proliferation or death, providing a deeper understanding of the pathological mechanisms in autoimmune myocarditis." (PMID 40778471, 2025).